TPH2 (tryptophan hydroxylase 2)
Diseases named in the same sentence as TPH2 in open-access papers (continued):
Sharing a sentence is not in itself a finding about the gene and the disease.
Obesity (7 papers, 2012 to 2025). Accumulation of substantial excess body fat. "In summary, our study demonstrates that obesity-associated increases in adipocyte TPH2 can regulate distal tissue physiology and energy metabolism, suggesting that TPH2 could be a potential therapeutic target for obesity and its associated complications." (PMID 40455408, 2025). "The present data highlight how obesity regulates the expression of adipocyte TPH2 and its role in regulating both white and brown adipocytes and systemic energy metabolism, providing a cellular signaling pathway that links obesity-associated hyperinsulinemia to increased adipocyte TPH2 expression." (PMID 40455408, 2025). "To further investigate whether a HFD itself or obesity-associated changes result in dramatic upregulation in adipocyte Tph2 expression, we analyzed Tph2 mRNA levels in age-matched chow-fed C57BL/6J and ob/ob mice or C57BL/6J mice fed a HFD for 6 weeks." (PMID 40455408, 2025). "Taken together, these data suggest that adipocyte TPH2 in obese mice and humans may contribute to the peripheral role of 5-HT and obesity-associated metabolic complications." (PMID 40455408, 2025). "In summary, these data suggest that obesity-induced hyperinsulinemia increases expression of adipose tissue TPH2 in both obese mice and humans, which might contribute to increased circulating 5-HT and potentially the progression of obesity-associated metabolic complications." (PMID 40455408, 2025). "TPH2 mRNA levels of subcutaneous adipose tissue showed a positive linear correlation with fasting plasma AST and plasma insulin levels in humans, suggesting that obesity-induced hyperinsulinemia increases TPH2 expression in human adipose tissues." (PMID 40455408, 2025). "Obese mice and humans exhibit increased expression of adipocyte tryptophan hydroxylase 2, elevating local and circulating serotonin levels, which promote obesity and metabolic complications." (PMID 40455408, 2025). "We found that obesity-induced hyperinsulinemia upregulated adipocyte TPH2 expression via activation of mechanistic target of rapamycin complex 1 and SREBP1." (PMID 40455408, 2025). "We also found that incubating primary adipocytes with insulin robustly increased TPH2 expression, demonstrating that the dramatic upregulation of adipocyte TPH2 in obese mice is driven by obesity-induced hyperinsulinemia." (PMID 40455408, 2025). "Collectively, in DIO mice, inhibiting adipocyte expression of TPH2 improves obesity-induced glucose intolerance and insulin resistance." (PMID 40455408, 2025). "Here, we report that adipose tissue expression of TPH2 is dramatically elevated in mice with diet-induced obesity (DIO) and ob/ob mice, as well as in obese humans." (PMID 40455408, 2025). "Because obesity per se is associated with hyperinsulinemia and insulin plays a pivotal role as a regulator of crucial transcription factors, we hypothesized that obesity-induced hyperinsulinemia can upregulate adipocyte TPH2 expression." (PMID 40455408, 2025). "Both HFD-fed mice and chow-fed ob/ob mice had striking increases in Tph2 mRNA levels, suggesting obesity-associated pathways, not specific diets, are responsible for this upregulation." (PMID 40455408, 2025). "Specifically, previous studies have found that SNPs within Cdh23 were correlated with BMI, SNPs in Tph2 were correlated with obesity, SNPs in Prox1 were correlated with glucose metabolism, SNPs in Lipc were correlated with cholesterol, and SNPs in Pnpla3 were correlated with hepatic lipid content." (PMID 31262088, 2019). "While the low body weight of Tph2−/− contrasts previous findings and conclusions, observation of obesity in Tph2+/− (exhibiting reduced brain 5-HT) as reflected by excess abdominal and pericardial fat storage, particularly in Tph2+/− females beyond 24 weeks, concurs." (PMID 22912815, 2012).
Obesity (continued). "To assess the potential translational significance of obesity-induced adipose TPH2 expression, we examined the expression of TPH1 and TPH2 in lean and obese humans." (PMID 40455408, 2025). "Conversely, TPH2 overexpression in epididymal adipocytes of chow-fed mice raised adipose and plasma 5-HT levels, suppressed BAT thermogenesis, and exacerbated obesity and metabolic dysfunction." (PMID 40455408, 2025). "One study compared the differences in DRN levels of the enzyme tryptophan hydroxylase 2 (TPH2, critical for serotonin synthesis) in the DIO and agouti models of obesity." (PMID 35023323, 2022). "On the other hand, agouti mice showed a significant increase of TPH2 expression (+42%) in the VTA, which might be a possible compensatory serotonin response to genetic melanocortin obesity in these mice." (PMID 35023323, 2022). "Overexpressing adipocyte TPH2 is sufficient to induce obesity without HFD feeding." (PMID 40455408, 2025).
anxiety disorder (6 papers, 2012 to 2023). A category of psychiatric disorders which are characterized by anxious feelings or fear often accompanied by physical symptoms associated with anxiety. "The third study on severe anxiety disorder (SAD) found that polymorphisms in two serotonin-related genes, the serotonin transporter-linked polymorphic region (5-HTTLPR) and the G703T polymorphism of tryptophan hydroxylase-2, had a significant effect on placebo." (PMID 23110189, 2012).
epilepsy (6 papers, 2015 to 2025). A brain disorder characterized by episodes of abnormally increased neuronal discharge resulting in transient episodes of sensory or motor neurological dysfunction, or psychic dysfunction. "Both EPI/SDOC + rats and DBA/2 mice that present with audiogenic-induced seizure followed by fatal respiratory arrest—a model of sudden and expected death in epilepsy—had increased transcript levels of tryptophan hydroxylase 2 and 5-HT presynaptic transporter." (PMID 35715469, 2022). "Thus, the second objective of our study was to investigate brainstem 5-HT system alterations related to epilepsy in Pilo-SE rats by measuring the number of 5-HT-positive cell bodies, the density of 5-HT-positive terminals, and TPH2 and SERT mRNA levels." (PMID 35715469, 2022). "In cresyl violet sections, there was a positive correlation between VLM neuronal density and duration of epilepsy (P < 0.01) and a trend for higher TPH2 neuronal counts in epilepsy patients with epilepsy duration of >10 years compared to cases with epilepsy onset <2 years (P ≤ 0.05)." (PMID 29608654, 2018). "These microdeletions affected 158 protein-coding RefSeq genes and exhibited an enrichment of genes previously associated with epilepsy (NRXN1, RBFOX1, PCDH7, KCNA2, EPM2A, RORB, PLCB1) and neuropsychiatric disorders (DPYD, CADM2, PARK2, GRM8, TSNARE1, TPH2, MACROD2)." (PMID 25950944, 2015).
obsessive-compulsive disorder (6 papers, 2007 to 2025). A disorder characterized by the presence of persistent and recurrent irrational thoughts (obsessions), resulting in marked anxiety and repetitive excessive behaviors (compulsions) as a way to try to decrease that anxiety. "Evidence of TPH2 variations playing a role in cognition comes from studies implicating TPH2 in the pathophysiology of ADHD and obsessive compulsive disorder." (PMID 27069689, 2016).
heroin addiction (4 papers, 2011 to 2021). "This TPH2 variant has also been associated with heroin addiction and quality of life in the MMT population." (PMID 32481444, 2020). "The genetic variants in TPH1 and TPH2 have been reported to be associated with alcoholism, nicotine dependence, and heroin addiction." (PMID 30059533, 2018). "Conversely, haplotypes of TPH2 (rs4570625, rs7963720, rs4760816, rs7305115, rs4290270, and rs17110747) were associated with heroin addiction." (PMID 30059533, 2018). "A recent study of heroin addiction also showed an association with TPH2 variants in Hispanics and African-Americans." (PMID 21886586, 2011). "Several variants in TPH2 have previously been associated with heroin addiction in African Americans and in Hispanics, and are also associated with phenotypes related to smoking status, neuropsychiatric disorders, higher reward dependence, and personality traits." (PMID 33915886, 2021). "Our study identified variations in five candidate genes, including GRIN3A, GRIN3B, CYP2C19, TPH2, and COMT, contributing to susceptibility to heroin addiction." (PMID 33915886, 2021). "Glutamate receptor metabotropic 6 (GRM6) and tryptophan hydroxylase 2 (TPH2) have also been reported to be involved in heroin dependence." (PMID 30059533, 2018). "The disparity between these results and the previously reported results for heroin addiction suggest that the TPH2 gene has little effect in psychostimulants with the characteristics of indirect dopaminergic agonists." (PMID 21886586, 2011).
mental disorder (4 papers, 2020 to 2025). A disease that has its basis in the disruption of mental process. "TPH2 is typically decreased in stability and catalytic activity in patients; thus, screening of molecules capable of binding and stabilizing the structure of TPH2 in activated conformation is desired for drug development in mental disorder treatment." (PMID 36046836, 2022). "Our research might shed light on the development of novel drugs targeting TPH2 for the treatment of mental disorders." (PMID 36046836, 2022). "Patrick and Ames's studies on patients with mental disorders have illustrated that vitamin D has a regulatory effect on tryptophan hydrolysis enzymes, indicating that more tryptophan is converted to serotonin in the brain by increasing the activity of the TPH2 enzyme." (PMID 33013260, 2020).
cocaine addiction (3 papers, 2011 to 2020). "TPH2 rs4290270 A>T polymorphism was related to the efficacy of disulfiram treatment for cocaine addiction." (PMID 30059533, 2018).
Intellectual disability (3 papers, 2014 to 2024). "HPA can be treated by Phe-deficient diet and the intellectual disabilities and parkinsonism are ameliorated by treatment with direct precursors for serotonin and dopamine, thereby circumventing the activities of TPH2 and TH, respectively." (PMID 39695187, 2024). "Altered RNA editing levels of both the glutamate receptor GRIK2 and the tryptophan hydroxylase TPH2 were also found in the brain of patients with psychiatric disorders and intellectual disability has been reported in patients with ADAR1 mutations." (PMID 24637888, 2014). "In addition, stressed Tph2+/− mice displayed upregulated Nono regulon, whose protein product has been characterized as an transcriptional regulator implicated in intellectual disability in humans as well as cognitive and affective deficits in mice." (PMID 37542675, 2023).
migraine (3 papers, 2011 to 2024). "Although this study does not support TPH2 as a key player in the migraine circuit TPH2 is emerging as a therapeutic target for stress disorders and abnormalities in TPH activity have been implicated in a variety of psychiatric disorders." (PMID 28194570, 2017).
alcohol abuse (2 papers, 2016 to 2023). The use of alcoholic beverages to excess, either on individual occasions ("binge drinking") or as a regular practice. "This upregulation in TPH2 expression was more pronounced in AD patients with a positive family history of alcohol abuse, suggesting that genetic factors may contribute to the observed alteration." (PMID 36833340, 2023). "The present study explored the relationship between SLC6A4, TPH2, and GALM genes and neurocognitive impairment in HIV-infected alcohol abusers." (PMID 27069689, 2016).
autoimmune disease (2 papers, 2024 to 2025). A disorder resulting from loss of function or tissue destruction of an organ or multiple organs, arising from humoral or cellular immune responses of the individual to their own tissue constituents. "Next, we determined the frequency of 4 Tph subsets (Tph1, Tph2, Tph17, and Tph1-17 cells) within CD45RA- memory CD4+ T cells in the blood of patients with various autoimmune diseases including SLE and healthy controls (HC)." (PMID 38448723, 2024).
breast carcinoma (2 papers, 2017 to 2023). "Noteworthy associations (BFDP < 0.8) between individual SNPs and breast-cancer risk have been identified particularly for TPH2 intronic polymorphisms." (PMID 37789226, 2023). "The involvement of TPH2 as a putative breast cancer susceptibility locus is plausible, as the enzyme is exclusively expressed in neuronal cells of the central nervous system where it catalyzes the rate limiting step in serotonin (5-HT) biosynthesis, the chemical precursor of melatonin." (PMID 37789226, 2023). "Hence, our findings of an association between TPH2 variants and increased breast-cancer risk are well in line with the notion that such variants impact on serotonin formation, thereby disrupting the SCN pacemaker circuitry feedback." (PMID 37789226, 2023). "In particular, the observed increased breast-cancer risk in TPH2 variant carriers may result from modified brain melatonin levels due to a dysfunctional SCN (together with reduced melatonin levels in the retina) that upon light-at-night periods may reduce pineal melatonin secretion." (PMID 37789226, 2023). "In line with the light-at-night hypothesis that links shift work with elevated breast-cancer risks our results point to SNPs in TPH2 and MAPK-genes that may impact the intricate network of circadian regulation." (PMID 37789226, 2023). "The triple interaction of TPH2 rs1386483 and rs1473473 as well as RAF1 rs3729931 increased breast-cancer risk by 20%, a dual interaction of MAPK8 rs10857561 and MAP2K1 rs1347069 by 15%, and MAPK8 rs10857561 alone by 11% (all observed at a prior probability of 0.01)." (PMID 37789226, 2023). "Given that serotonin promotes the proliferation and survival of breast cancer cells, the upregulation of TPH2 in astrocytes might contribute to cancer cell growth in brain tissue through increased serotonin production." (PMID 28210624, 2017). "The observed interactions between genetic variants of TPH2 and MAPK8 highlight their cooperation as putative breast-cancer risk modulators and call upon the comprehensive scrutiny of the circadian clock system and its input and output effectors in large breast-cancer cohorts." (PMID 37789226, 2023).
colitis (2 papers, 2021 to 2026). Inflammation of the colon. "Conversely, in the hippocampus, AmEVs reversed the colitis-induced decline in 5-HT levels, accompanied by upregulated expression of Tph2, the rate-limiting enzyme for 5-HT production." (PMID 41496520, 2026). "This bidirectional effect paralleled changes in the gene expression of Tph2, showing decreased levels in colitis mice and significant upregulation following AmEVs treatment." (PMID 41496520, 2026). "The difference between TpH1−/− mice TpH2−/− mice in the severity of colitis due to reduced levels of enteric 5-HT and reduced neuronal 5-HT, respectively, indicates that 5-HT can have different effects depending on the location." (PMID 34502396, 2021). "A further study showed that TpH2−/− mice with DSS-induced colitis had increased severity of disease characterized by an increased secretion of the pro-inflammatory cytokines IL-1β, IL-6 and, TNF-α, and high mortality rates in comparison to the wild type." (PMID 34502396, 2021).
colorectal cancer (2 papers, 2025). A primary or metastatic malignant neoplasm that affects the colon or rectum. "Meanwhile, Tph2 is significantly upregulated in the core region of colorectal cancer tumors, and conditional knockout of Tph2 in intestinal epithelial cells markedly suppresses tumorigenesis in a murine intestinal cancer model." (PMID 41488637, 2025). "In colorectal cancer models, knockout of TPH2 significantly suppresses tumor growth, suggesting that TPH2-positive neurons in the gut promote cancer stem cell (CSC) proliferation through 5-HT secretion." (PMID 40666095, 2025).
developmental delays (2 papers, 2015 to 2026). "Here, we investigated, therefore, whether Tph2 null mutant mouse pups display deficits in isolation-induced USV, the most commonly studied behavioral measure to assess developmental delays and communication deficits in rodent models for ASD." (PMID 25901271, 2015). "Interestingly, during prenatal development, we did not see differences in body weight in Tph2-/- mice and Tph2+/+ controls, indicating that the developmental delay emerges after birth." (PMID 25901271, 2015).
glioma (2 papers, 2014 to 2022). A benign or malignant brain and spinal cord tumor that arises from glial cells (astrocytes, oligodendrocytes, ependymal cells). "However, mRNA levels of RE-1 silencing transcription factor, REST, which has been proposed as a transcriptional regulator of tph2 through bipartite neuron-restrictive silencing element in glioma cells was not altered." (PMID 24416346, 2014).
injury (2 papers, 2010 to 2023). Damage inflicted on the body as the direct or indirect result of an external force, with or without disruption of structural continuity. "We found that childhood trauma and TPH2 rs7305115 interacted in both behaviour and the GMV of brain subregions." (PMID 38093326, 2023). "The expression of Tph2 in the dorsal root ganglia (DRGs) increased after peripheral nerve injury of the sciatic nerve in the Spared Nerve Injury model (SNI) in C57Bl/6 mice." (PMID 20977736, 2010).
lupus (2 papers, 2024 to 2025). "Study found that Tph1 and Tph17 cells showed B-helper functions, while Tph2 cells exhibited cytotoxic activity in systemic lupus erythematosus patients." (PMID 40599793, 2025). "In contrast, Tph2 subset is shown to possess low B cell helper activity but express cytotoxic function-related molecules and may be contribute to the tissue injury of lupus nephritis in addition to cutaneous and musculoskeletal manifestations in SLE." (PMID 38448723, 2024). "When SLE patients with skin or musculoskeletal manifestations became lupus low disease activity state (LLDAS) by the treatment with medications, the frequency of Tph1 and Tph2 cells, like whole Tph cells, were reduced significantly as compared with that before the treatment." (PMID 38448723, 2024).
lupus nephritis (2 papers, 2024 to 2025). Glomerulonephritis in the context of systemic lupus erythematosus. "By contrast, Tph2 cells appeared to be involved in lupus nephritis, cutaneous manifestation, and musculoskeletal manifestation via CX3CR1-CX3CL1 axis." (PMID 38448723, 2024). "Furthermore, the percentages of Tph2 cells were also reduced markedly when patients with lupus nephritis became LLDAS." (PMID 38448723, 2024). "Based on these findings, it is plausible that CX3CR1-positive Tph2 cells can preferentially migrate into lupus kidney via CX3CR1-CXCL1 axis and contribute to the lupus nephritis in combination with CD16+ monocytes." (PMID 38448723, 2024).
neuroblastoma (2 papers, 2021 to 2023). Neuroblastoma (NB) is the most common solid, extracranial childhood tumor. "Interestingly, we observed that D-mannose significantly increased TPH2 expression in a dose-dependent manner in SH-SY5Y human neuroblastoma cells." (PMID 37914710, 2023).
psychosis (2 papers, 2011 to 2014). "We analyzed the association between the variations in the brain tryptophan hydroxylase 2 (TPH2) gene, a rate limiting enzyme for serotonin biosynthesis, and methamphetamine (METH) dependence/psychosis in a Japanese population." (PMID 21886586, 2011). "Despite the strong scientific rationale for studying polymorphisms in the TPH2 gene in METH dependence/psychosis, we could not identify any variants or haplotypes associated with the phenotype." (PMID 21886586, 2011). "Our results indicate that the TPH2 gene variations may not be vulnerability factors in METH dependence/psychosis, and indeed that they are likely to make a small or no contribution to the development of METH dependence/psychosis." (PMID 21886586, 2011).